RNU6-587P (RNA, U6 small nuclear 587, pseudogene)
Gene: Small nuclear RNA gene on chromosome X (101,691,580 to 101,691,685, forward strand). Ensembl gene ENSG00000212584.
Homologues: Orthologues: chimpanzee U6 (99% identical), macaque U6 (95% identical), pig U6 (86% identical). Paralogues in human: RNU6-1152P (86% identical), RNU6-203P (86% identical), RNU6-1141P (85% identical), RNU6-41P (85% identical), RNU6-562P (85% identical), RNU6-820P (85% identical), RNU6-1060P (84% identical), RNU6-1131P (84% identical), RNU6-115P (84% identical), RNU6-15P (84% identical), RNU6-166P (84% identical), RNU6-199P (84% identical), and 1290 more.